COLEC11 (collectin subfamily member 11)
Description:
Lectin that plays a role in innate immunity, apoptosis and embryogenesis. Calcium-dependent lectin that binds self and non-self glycoproteins presenting high mannose oligosaccharides with at least one terminal alpha-1,2-linked mannose epitope. Primarily recognizes the terminal disaccharide of the glycan. Also recognizes a subset of fucosylated glycans and lipopolysaccharides. Plays a role in innate immunity through its ability to bind non-self sugars presented by microorganisms and to activate the complement through the recruitment of MAPS1. Also plays a role in apoptosis through its ability to bind in a calcium-independent manner the DNA present at the surface of apoptotic cells and to activate the complement in response to this binding (Probable). Finally, plays a role in development, probably serving as a guidance cue during the migration of neural crest cells and other cell types during embryogenesis.
Synonyms: CL-K1; MGC3279; CL-11; 3MC2; CL-K1-I; CL-K1-II; CL-K1-IIa; CL-K1-IIb; CLK1
Tractability: Antibody: UniProt places it where antibodies can reach, with high confidence; its Gene Ontology location is reachable by antibodies, with high confidence; UniProt predicts a signal peptide or a membrane-spanning region.
Gene: Protein-coding gene on chromosome 2 (3,592,791 to 3,644,649, forward strand). Ensembl gene ENSG00000118004.
Subcellular location: Secreted
Pathways (Reactome):
Immune System: Initial triggering of complement; Lectin pathway of complement activation
Vesicle-mediated transport: Scavenging by Class A Receptors
Gene Ontology:
Molecular function: calcium ion binding; calcium-dependent carbohydrate binding; D-mannose binding; DNA binding; fucose binding; identical protein binding; oligosaccharide binding; protein binding
Biological process: antimicrobial humoral response; complement activation; complement activation, lectin pathway; positive regulation of opsonization; proteolysis; cell surface pattern recognition receptor signaling pathway; developmental process; execution phase of apoptosis
Cellular component: extracellular region; external side of plasma membrane; serine-type endopeptidase complex
Genetic constraint (gnomAD): Loss-of-function variants: 20 observed, 24.89 expected, observed/expected ratio (o/e) 0.8, 90% interval 0.56 to 1.17. The upper end of that interval is the gene's LOEUF score, 1.17, which puts it in group 5 of 6, group 1 being the genes least tolerant of losing a copy. Missense variants: 288 observed, 372.67 expected, observed/expected ratio (o/e) 0.77, 90% interval 0.7 to 0.85. Synonymous variants: 155 observed, 152.61 expected, observed/expected ratio (o/e) 1.02, 90% interval 0.89 to 1.16.
Homologues: Orthologues: chimpanzee COLEC11 (99% identical), mouse Colec11 (92% identical), rat Colec11 (91% identical), guinea pig COLEC11 (88% identical), dog COLEC11 (87% identical), pig COLEC11 (84% identical), tropical clawed frog colec11 (76% identical), zebrafish colec11 (69% identical). Paralogues in human: COLEC10 (46% identical), SFTPD (32% identical), SFTPA1 (24% identical), SFTPA2 (24% identical).
Diseases named in the same sentence as COLEC11 in open-access papers:
COLEC11 is named in the same sentence as 62 diseases in open-access papers, as found by Europe PMC text mining. Sharing a sentence is not in itself a finding about the gene and the disease. The quoted sentences say what the papers report.
3MC syndrome (8 papers, 2014 to 2024). "We report the case of a four-year-old female with 3MC syndrome who was diagnosed with a confirmed mutation in the COLEC11 gene." (PMID 34589314, 2021). "3MC syndrome is a rare genetic disorder inherited through an autosomal recessive inheritance pattern caused by mutations in one of three genes: COLEC11, COLEC10, and MASP1." (PMID 34589314, 2021). "This may be supported by the relationship between MASP1/3, COLEC10, and COLEC11 mutations and the incidence of 3MC syndrome, associated with craniofacial abnormalities." (PMID 32751929, 2020). "This is supported by relationships between MASP1/3, COLEC10, and COLEC11 gene mutations and the incidence of 3MC syndrome, associated with craniofacial abnormalities such as radioulnar synostosis high-arched eyebrows, cleft lip/palate, hearing loss, and ptosis." (PMID 32751929, 2020). "As mentioned, so far 11 mutations in the COLEC11 gene, three in the COLEC10 gene, and 16 in the MASP1/3 gene associated with 3MC syndrome have been described." (PMID 32751929, 2020). "Several different potentially deleterious mutations in genes of the lectin arm of the complement system - such as MASP1, COLEC10, and COLEC11 genes – have been described in patients with 3MC syndrome." (PMID 32116493, 2020). "To date, 16 mutations in MASP-1/3, 12 mutations in COLEC11 and three in COLEC10 associated with 3MC syndrome have been identified." (PMID 32751929, 2020). "We previously reported that mutations in COLEC11 and MASP1/3 genes were responsible for several cases of 3MC syndrome." (PMID 28301481, 2017). "We previously demonstrated that mutations in COLEC11 and MASP1/3 lectin complement pathway related genes are causative of 3MC syndrome in 11 families and 16 patients." (PMID 28301481, 2017). "We previously reported that lectin complement pathway genes COLEC11 and MASP1/3 were mutated in 3MC syndrome patients." (PMID 28301481, 2017). "We previously reported that lectin complement pathway genes COLEC11 and MASP1/3 are mutated in 3MC syndrome patients." (PMID 28301481, 2017). "Further studies, however, are necessary to better understand the mechanisms by which dysfunction of MASP1/3, COLEC10, and COLEC11 genes may lead to the 3MC syndrome." (PMID 32751929, 2020). "Further studies, however, are necessary to further understand the mechanisms by which dysfunctional MASP1, COLEC10, and COLEC11 genes may lead to 3MC syndrome." (PMID 32116493, 2020). "It should be however mentioned, that mice with knockout in MASP1/3 or COLEC11 genes developed normally and no defects similar to 3MC syndrome were noticed." (PMID 32751929, 2020).
Chagas disease (3 papers, 2019 to 2025). A parasitic infection caused by Trypanosoma cruzi. "COLEC11 rs7567833G and MASP2 Chagas disease risk genotypes may act synergistically to increase the risk of developing CCC Chagas disease." (PMID 40297326, 2025). "Certain genotypes of COLEC11 in rs7567833, rs7567833, and rs7567833 and the COLEC11⁣∗GGC haplotype were associated with T. cruzi infection and progression to CCC and cardio-digestive forms of Chagas disease." (PMID 40297326, 2025). "A cohort study on 251 patients with Chagas disease in Brazil found that genetic variations in COLEC11 and MASP2 contributed to the pathogenesis of Chagas disease, which is characterized by dilated cardiomyopathy." (PMID 41155225, 2025).
Intellectual disability (3 papers, 2015 to 2023). "Mutations in COLEC11 may cause 3M syndrome, which is associated with craniofacial dysmorphism, intellectual disability, and genital, renal, and limb abnormalities." (PMID 37273692, 2023).
schistosomiasis (3 papers, 2015 to 2023). An infectious disease caused by parasitic trematodes of the genus Schistosoma that colonize human blood vessels and release eggs that can cause granulomatous reactions leading to acute (swimmer's itch or acute schistosomiasis syndrome) or chronic disease. "The reconstructed COLEC11*TCCA haplotypes were associated with higher CL-K1 serum levels (P = 0.002) and with decreased schistosomiasis (OR = 0.38, 95%CI = 0.23–0.63, Pcorr = 0.0001)." (PMID 25807310, 2015). "Stratification of our study group based on reconstructed COLEC11 haplotypes revealed that the frequency of the COLEC11*TCCG haplotype was significantly more frequent in the infection group than in controls, suggesting that individuals with these haplotypes had a higher risk of schistosomiasis." (PMID 25807310, 2015).
melanoma (2 papers, 2023 to 2025). A malignant, usually aggressive tumor composed of atypical, neoplastic melanocytes. "Collectively, these results demonstrate that Colec11–/– mice have a higher lymphocytes/myeloid lineage cells ratio and a better cytotoxic T cell infiltration in the melanoma." (PMID 36883567, 2023). "Significantly higher levels of Ifng, Nos2, Il12, Ccl5, Cx3cl1, and Cxcl9 — and, by contrast, significantly lower levels of Arg1 — were detected in the melanomas of Colec11–/– mice, compared with WT mice." (PMID 36883567, 2023). "M1/M2 phenotypes of TAMs in the melanomas of WT and Colec11–/– mice were further evaluated by IHC costaining of CD206/CD68 or H2-Ab1/CD68." (PMID 36883567, 2023). "Costaining analysis of CD206/CD68 showed that the melanomas of Colec11–/– mice exhibited lower numbers of CD68+ cells than WT controls." (PMID 36883567, 2023). "Quantitative PCR (qPCR) showed that Colec11 mRNA was detected in the melanomas of both WT and Colec11–/– mice; however, significantly higher expression was observed in WT mice, compared with Colec11–/– mice." (PMID 36883567, 2023). "Having demonstrated the role of CL-11 in promoting melanoma growth by using Colec11–/– mice, we next sought to explore therapeutic potential of targeting CL-11 in melanoma growth." (PMID 36883567, 2023). "Analysis of open data sets revealed that COLEC11 gene expression is upregulated in human melanomas and that high COLEC11 expression has a trend toward poor survival." (PMID 36883567, 2023). "Costaining analysis of MHC class II (H2-Ab1)/CD68 showed that the melanomas of Colec11–/– mice exhibited lower numbers of CD68+ cells again but higher percentage of H2-Ab1+ cells and higher intensity of H2-Ab1 in CD68+ cells than WT controls." (PMID 36883567, 2023). "More CD3+ infiltrates and fewer CD11b+ infiltrates were also observed in Colec11–/– mice when YUMM1.7 melanoma model was used." (PMID 36883567, 2023). "To determine the role of CL-11 in tumor growth, we assessed tumor growth in Colec11–/– mice and their WT littermates after s.c. inoculation with B16 melanoma cells by performing bioluminescence imaging and measuring tumor volume and weight." (PMID 36883567, 2023). "We therefore performed RNA-Seq in TAMs isolated from melanomas of WT and Colec11–/– mice by sorting CD45+F4/80+ cells by FACS." (PMID 36883567, 2023). "COLEC11 gene expression levels were significantly elevated in melanomas compared with normal skin in all 4 data sets." (PMID 36883567, 2023). "By analyzing COLEC11 gene expression in human melanomas using multiple online data sets, we revealed that COLEC11 gene expression is significantly upregulated in melanomas." (PMID 36883567, 2023). "A lower percentage of CD25+ cells within the CD4+ T cell compartment was detected in melanomas of Colec11–/– mice compared with WT mice." (PMID 36883567, 2023). "Colec11–/– mice have reduced melanoma cell proliferation and angiogenesis." (PMID 36883567, 2023). "Furthermore, we evaluated the relevance of CL-11 in human melanomas by analyzing COLEC11 gene expression in human melanomas and its association with patient survival using several open data sets and assessing whether CL-11 has stimulatory effects on human melanoma cells in vitro." (PMID 36883567, 2023). "In doing this, we performed several cellular and molecule analyses using excised B16 melanomas from WT and Colec11–/– mice to assess: (a) composition of tumor-infiltrating leukocytes, (b) intratumor gene expression of cytokines/chemokines, and (c) phenotype of tumor-associated macrophages (TAMs)." (PMID 36883567, 2023). "Furthermore, we evaluated the correlation of COLEC11 expression with survival of patients with melanoma using the data set obtained from TCGA SKCM." (PMID 36883567, 2023). "CD31 and VWF were markedly reduced in melanomas of Colec11–/– mice compared with WT mice." (PMID 36883567, 2023).
melanoma (continued). "It is still possible that the differential expression of the COLEC11 gene among patients with melanoma alone does not dictate survival; instead, it is a factor that allows melanoma to originate and proliferate." (PMID 36883567, 2023). "Cellular sources of CL-11 in the melanoma were further analyzed by qPCR in CD45+ (immune-infiltrating) cells and CD45– (nonimmune) cells obtained from melanomas of WT and Colec11–/– mice by FACS." (PMID 36883567, 2023).
Schistosoma haematobium infection (2 papers, 2015 to 2019). "This study investigated the association between serum CL-K1 level and functional genetic variants in the COLEC11 gene in urinary schistosomiasis." (PMID 25807310, 2015). "The COLEC11 homozygous genotype of the minor allele rs7567833-AA was observed significantly less often in the SEP group than in the SELN group (OR = 0.2, 95%CI = 0.08–0.90,Pcorr = 0.01), showing an association with decreased risk of urinary schistosomiasis." (PMID 25807310, 2015).
autoimmune disease (1 paper, 2021). A disorder resulting from loss of function or tissue destruction of an organ or multiple organs, arising from humoral or cellular immune responses of the individual to their own tissue constituents. "Eleven proteins (increased: ATP5B, CALML5, COLEC11, FCGBP, PLEK, PLXND1; decreased: APOB, ATP8B1, FAM20C, LOXL3, TIMD4) were significantly altered in bvFTD with autoimmune disease compared to those without autoimmune disease." (PMID 34539672, 2021).
cardiomyopathy (1 paper, 2019). A disease of the heart muscle or myocardium proper. "Considering the biological relevance between collectin-11 and MASP2 and that MASP2 genetic variants were associated with high risk of cardiomyopathy in chronic CD, the genetic interaction between COLEC11 and MASP2 variants were analyzed." (PMID 30995222, 2019). "Patients with cardiomyopathy had a higher frequency of COLEC11*GGC haplotype, carrying the rs7567833G allele (p = 0.022, OR 2.2, 95% CI 1.1–4.5) than controls." (PMID 30995222, 2019). "Also, the minor allele G (rs7567833G), its genotypes (rs7567833AG and rs7567833GG) and COLEC11*GGC haplotype were associated with cardiomyopathy." (PMID 30995222, 2019). "COLEC11 genotypes and alleles frequencies in patients with chronic CD based on cardiomyopathy." (PMID 30995222, 2019). "COLEC11 and MASP2*CD risk genotypes were associated with cardiomyopathy (p = 0.014; OR 9.3, 95% CI 1.2–74) and with the cardiodigestive form of CD (p = 0.005; OR 15.2, 95% CI 1.7–137), suggesting that both loci act synergistically in immune modulation of the disease." (PMID 30995222, 2019). "The frequency of the risk genotypes in both loci (COLEC11 AG+GG and MASP2*CD+ carriers) was higher in patients with cardiodigestive form (21%) and cardiomyopathy (13%), than healthy controls (2%), (p = 0.005, OR 15.2, 95% CI 1.7–137; p = 0.014, OR 9.3, 95% CI 1.2–74, respectively)." (PMID 30995222, 2019).
fetal growth restriction (1 paper, 2024). A fetus that does not grow beyond the 10th percentile of conventionally accepted weight for gestational age. "Lower median CL-10 was associated with fetal growth restriction, while COLEC11 heterozygosity for a polymorphism affecting CL-11 activity was more common in pPROM, compared with the corresponding reference groups." (PMID 39464884, 2024).
fibrosis (1 paper, 2025). the formation of excess fibrous connective tissue in an organ or tissue in a reparative or reactive process. "Thus, given its high feature importance in the models and its known biological role in fibrosis, COLEC11 was selected as a compelling second candidate for clinical validation." (PMID 40869127, 2025).
glomerulosclerosis (1 paper, 2022). A hardening of the kidney glomerulus caused by scarring of the blood vessels. "In the transcriptomics analyses, as expected, all 13 significant correlations with the level of fibrosis were observed for tubular gene expression, and the two observed correlations for glomerulosclerosis were for glomerular expression of SNX30 and COLEC11." (PMID 35763030, 2022).
heart failure (1 paper, 2019). Inability of the heart to pump blood at an adequate rate to meet tissue metabolic requirements. "In addition, COLEC11*GGC was significantly associated with patients presenting ECHO alterations and with heart failure (p = 0.044, OR 2.2, 95% CI 1.0–4.6; and p = 0.033, OR 2.5, 95% CI 1.1–5.6 respectively) in comparison to controls." (PMID 30995222, 2019).
hepatocellular carcinoma (1 paper, 2022). A malignant tumor that arises from hepatocytes. "Our results provide an insight into the possible mechanism by which COLEC11 regulates the early recurrence of hepatocellular carcinoma via plasma sEVs." (PMID 36471393, 2022).
liver fibrosis (1 paper, 2023). "The results implied the mRNA expression of Colec11 and Colec10 were downregulated in the hepatic stellate cells in the early phase of liver fibrosis." (PMID 38036508, 2023). "Since the Colec10 and Colec11 were highly expressed in the qHSCs, we assumed the two C-type lectins could be involved in the pathology of liver fibrosis." (PMID 38036508, 2023).
metastatic melanoma (1 paper, 2023). A melanoma that has spread from its primary site to another anatomic site. "We also analyzed COLEC11 gene expression in primary and metastatic melanomas and found higher levels in metastatic melanomas." (PMID 36883567, 2023).
ovarian carcinoma (1 paper, 2010). A malignant neoplasm originating from the surface ovarian epithelium. "For example, in ovarian cancer it is accompanied by sharp downregulation of genes COLEC11, PEG3 and TSPAN8, which is not the case in other cancers." (PMID 21047417, 2010).
rheumatoid arthritis (1 paper, 2025). A chronic, systemic autoimmune disorder characterized by inflammation in the synovial membranes and articular surfaces. "Furthermore, the upregulation of COLEC11 may provide a new strategy for treating rheumatoid arthritis and other inflammatory diseases by promoting the expression of the anti-inflammatory factor IL-10 and suppressing the activation of antigen-presenting cells." (PMID 40705171, 2025).
Varicose veins (1 paper, 2023). Enlarged and tortuous veins. "As a result, eight proteins were found to be causally associated with varicose veins, including COLEC11, IRF3, LUM, POSTN, RPN1, RSPO3, SARS2, and VAT1." (PMID 37404740, 2023). "We identified eight plasma proteins that are significantly associated with the risk of varicose veins after Bonferroni correction (P < 2.495 × 10−5), with five being protective (LUM, POSTN, RPN1, RSPO3, and VAT1) and three harmful (COLEC11, IRF3, and SARS2)." (PMID 37404740, 2023). "The colocalization analysis indicated that COLEC11, IRF3, LUM, POSTN, RSPO3, and SARS2 shared the same causal variant with varicose veins." (PMID 37404740, 2023). "The COLEC11, IRF3, LUM, POSTN, RSPO3, and SARS2 were considered to share the same variant of varicose veins." (PMID 37404740, 2023).
cancer (5 papers, 2010 to 2025). A tumor composed of atypical neoplastic, often pleomorphic cells that invade other tissues. "We found the COLEC11 were expressed in both of cancer tissues and noncancer tissues, but the noncancer tissue had a higher expression of COLEC11." (PMID 38036508, 2023).